NUDCP2 (nuclear distribution C pseudogene 2)
Gene: Processed pseudogene on chromosome 2 (178,454,716 to 178,455,428, forward strand). Ensembl gene ENSG00000238082.
Diseases named in the same sentence as NUDCP2 in open-access papers:
NUDCP2 is named in the same sentence as 1 disease in open-access papers, as found by Europe PMC text mining. Sharing a sentence is not in itself a finding about the gene and the disease.
NUDCP2 shares sentences with these, for which no sentence is quoted: serous ovarian cancer (1 paper).